ALB (albumin)
Diseases named in the same sentence as ALB in open-access papers (continued):
Sharing a sentence is not in itself a finding about the gene and the disease.
lung cancer (269 papers, 1995 to 2026). A malignant neoplasm involving the lung. "This study evaluated the associations between serum creatinine and representative endogenous antioxidant biomarkers such as bilirubin, albumin, and uric acid and the risk of lung cancer, stratified by smoking status." (PMID 40427466, 2025). "In conclusion, sustaining a suitable body mass index, improved levels of serum albumin, and a decreased neutrophil-to-lymphocyte ratio can lead to an elevated advanced lung cancer inflammation index, which is associated with a more favorable prognosis." (PMID 39036488, 2024). "CRA in lung cancer patients with decreased serum iron is primarily associated with albumin, age, and cancer staging, while CRA in lung cancer patients with normal serum iron is mainly related to CRP, albumin, total cholesterol, and cancer staging." (PMID 38562035, 2024). "In contrast, albumin-bound paclitaxel demonstrated a low risk of TIP in patients with lung cancer in one study where 95.7% of the patients were free of ILD exacerbation at the prespecified 28-day endpoint." (PMID 39302574, 2024). "Tilman Kühn and colleagues found that lower serum albumin levels were significantly associated with increased mortality from breast, prostate, colorectal, and lung cancer." (PMID 38500655, 2024). "Some studies have reported that albumin is associated with the prognosis of early‐stage lung cancer." (PMID 37793977, 2023). "No baseline characteristics including age, sex, smoking history, BMI, baseline albumin, emphysema, and 6MWT showed a relevant relation with significant weight loss, except comorbidity of lung cancer (odds ratio [OR] = 2.828, p = 0.047)." (PMID 37031256, 2023). "Low albumin, bilirubin, and raised liver enzymes/urate were associated with a raised risk of lung cancer for women with a smoking history." (PMID 36989955, 2023). "Low urate, bilirubin and albumin were associated with a raised risk of lung cancer for men with a smoking history." (PMID 36989955, 2023). "We also found that serum albumin was inversely associated with lung cancer risk overall and among African Americans." (PMID 35814479, 2022). "We also evaluated the associations of lung cancer risk with the total bilirubin/albumin ratio, a surrogate measurement of free bilirubin." (PMID 35814479, 2022). "This study investigated the associations of serum levels of total bilirubin and albumin with lung cancer risk among low-income Americans." (PMID 35814479, 2022). "Epidemiological studies reported that a low pretreatment albumin level was associated with poor outcome in lung cancer patients." (PMID 36316884, 2022). "Previous studies conducted among European and Asian decedents reported inverse associations of serum total bilirubin and albumin with lung cancer risk." (PMID 35814479, 2022). "Conditional logistic regression models were applied to evaluate the associations of total bilirubin and albumin with lung cancer risk." (PMID 35814479, 2022). "Another study also reported that one SD increment in albumin was inversely associated with lung cancer risk (HR=0.82, 95% CI: 0.72-0.94) among Koreans." (PMID 35814479, 2022). "Higher serum levels of albumin were significantly associated with decreased risk of lung cancer (ORT3 vs. T1 = 0.70, 95% CI: 0.50-0.98)." (PMID 35814479, 2022). "We found that higher albumin levels were associated with decreased risk of lung cancer overall and among African Americans." (PMID 35814479, 2022). "A previous study reported that higher levels of albumin had a marginally significant association with a lower risk of lung cancer (HR=0.72, 95% CI: 0.51-1.00)." (PMID 35814479, 2022). "Association of serum levels of total bilirubin and albumin with lung cancer risk by time between blood collection and lung cancer diagnosis." (PMID 35814479, 2022).
lung cancer (continued). "Serum levels of albumin were significantly associated with decreased risk of lung cancer overall (ORT3 vs. T1 = 0.70, 95% CI: 0.50-0.98) and among African Americans (ORT3 vs. T1 = 0.62, 95% CI: 0.41-0.96), but not among European Americans." (PMID 35814479, 2022). "The baseline C‐reactive protein:albumin ratio was significantly associated with overall survival in non‐small cell lung cancer patients treated with nivolumab monotherapy." (PMID 33434414, 2021). "Increase in IL-6, IL-10, NLR, PLR, and LDH levels or reduced ALC and ALB levels were associated with the occurrence of CIP in lung cancer patients." (PMID 34327140, 2021). "The baseline value of C‐reactive protein:albumin ratio was significantly associated with one‐year mortality and overall survival in non‐small cell lung cancer patients treated with nivolumab." (PMID 33434414, 2021). "For lung cancer, the inverse association was observed between lung cancer risk and albumin concentrations." (PMID 34041866, 2021). "The humanized IL-6Rab, tocilizumab, reduced plasma IL-6 levels, attenuated muscle loss, and restored levels of plasma albumin in lung cancer patients." (PMID 31010015, 2019). "In a systematic review, including 10 studies on lung cancer, the majority of studies identified that higher albumin is associated with increased survival, which is consistent with our results." (PMID 30941358, 2019). "In a systematic review, including 10 studies on lung cancer, the majority of studies identified that higher albumin is associated with increased survival." (PMID 30941358, 2019). "WBC count, hemoglobin, platelet and CRP levels are associated with poor prognosis in lung cancer, while low hemoglobin and albumin reflect poor nutritional status associated with cachexia in cancer patients." (PMID 30005083, 2018). "ALB is commonly used to represent the nutritional statuses of patients, and elevated serum ALB levels are associated with improved survival among lung cancer patients." (PMID 29268698, 2017). "Of the 10 lung cancer studies reviewed, nine reported that higher serum albumin levels were associated with improved survival." (PMID 26356222, 2015). "An elevated serum albumin level has been found to be associated with improved survival among patients with lung cancer." (PMID 26356222, 2015). "The Tromso study describing an association between albuminuria and cancer showed a 5.4-fold increase risk for lung cancers in patients with an albumin-to-creatinine ratio in the highest quintile." (PMID 24558629, 2013). "Consistent with studies reviewed under gastrointestinal and lung cancers, lower levels of serum albumin were associated with poor survival in all 6 studies." (PMID 21176210, 2010). "Of the 10 studies reviewed on lung cancer, all excepting one found higher serum albumin levels to be associated with better survival." (PMID 21176210, 2010). "Recently the combination of C-reactive protein and albumin, termed the mGPS, was shown to be associated in a similar manner in patients with lung cancer and predict cancer-specific survival in a number of operable and inoperable cancers." (PMID 20717110, 2010). "Additionally, plasma albumin a major antioxidant protein, has been inversely associated with lung cancer risk, suggesting its potential as a protective factor." (PMID 40719999, 2025). "Taken together, the observed inverse associations between total bilirubin and ALBI and lung cancer risk in men are biologically plausible given the interrelated pathways involving bilirubin–testosterone, albumin–testosterone, testosterone–lung cancer, and bilirubin–lung cancer." (PMID 40508934, 2025). "Furthermore, an increased albumin-to-fibrinogen ratio (AFR) has been linked to poor prognosis in several cancer types including lung cancer, bladder cancer and colorectal cancer." (PMID 40433663, 2025).
lung cancer (continued). "A one SD increase in albumin was significantly and negatively associated with lung cancer risk only among ever-smokers (HR: 0.878, 95% CI: 0.807–0.955, p = 0.0024), and this association remained significant in the overall male population (HR: 0.893, 95% CI: 0.825–0.968, p = 0.0059)." (PMID 40427466, 2025). "This large-scale prospective cohort study confirmed that total bilirubin, the Albumin–Bilirubin (ALBI) index, and the Platelet–Albumin–Bilirubin (PALBI) index are significantly associated with lung cancer risk, with the direction of these associations differing markedly between men and women." (PMID 40508934, 2025). "NAR, combining neutrophil counts and serum albumin count, is a novel and convenient available biomarker for systemic inflammation status and has been proven to be linked to major adverse events, such as aneurysmal subarachnoid hemorrhage and lung cancer." (PMID 38918991, 2024). "Univariate analysis shows that the differences in whether age, sex, different cancer staging, surgery, and albumin will cause the occurrence of CRA in lung cancer patients with decreased serum iron have statistical significance." (PMID 38562035, 2024). "Using a large cohort of UK residents (UK Biobank), we explored the clinical and economic value of LBTs (bilirubin, albumin, alanine aminotransferase, aspartate aminotransferase, alkaline phosphatase, gamma-glutamyl transferase) and urate in lung cancer risk prediction." (PMID 36989955, 2023). "Numerous predicted ratios and scores based on inflammatory associated variables, such as NLR, PLR, CRP/ALB, and modified Glasgow prognostic score (mGPS) have been applied to predict the prognosis of colorectal cancer, gastric cancer, lung cancer and other cancer." (PMID 37089594, 2023). "In this study, we investigated the associations of pre-diagnostic serum levels of total bilirubin and albumin with lung cancer risk in the Southern Community Cohort Study (SCCS), a cohort study comprised of a large proportion of low-income African and European Americans." (PMID 35814479, 2022). "Given a strong link of chronic infection and inflammatory microenvironment to lung cancer, the inverse associations of serum albumin that we observed in the current study could be biologically plausible." (PMID 35814479, 2022). "In addition, we found that higher levels of albumin were significantly inversely associated with lung cancer risk overall and among African Americans." (PMID 35814479, 2022). "Association of serum levels of total bilirubin and albumin with lung cancer risk by smoking status." (PMID 35814479, 2022). "Recently, the Kailuan cohort in China showed that pre-diagnostic albumin was inversely associated with lung cancer risk (HRQ4 vs. Q1 = 0.70, 95% CI: 0.52-0.95), but the inverse association became insignificant after excluding cases diagnosed within two years of enrollment." (PMID 35814479, 2022). "Association of serum levels of total bilirubin and albumin with lung cancer risk." (PMID 35814479, 2022). "Several prospective studies investigating the associations of total bilirubin and albumin levels with lung cancer risk have been conducted, and a meta-analysis indicated an inverse association between total bilirubin levels and risk of lung cancer." (PMID 35814479, 2022). "This could provide a unique insight into the associations of serum total bilirubin and albumin with lung cancer among underserved populations who are at a greater risk for lung cancer." (PMID 35814479, 2022). "However, the inverse association between lung cancer risk and serum albumin was novel and should be interpreted cautiously." (PMID 34041866, 2021). "Though the physiological and functional properties of the lung have little to do with albumin, the association between albumin and lung cancer risk may reflect systemic inflammation." (PMID 34041866, 2021).
lung cancer (continued). "Similarly, findings from the Southern Community Cohort Study in the United States showed that lower pre-diagnostic levels of total bilirubin and albumin were associated with an increased risk of lung cancer, with this pattern being particularly evident among smokers." (PMID 40508934, 2025). "However, [123I]BMIPP binds to >99% of serum albumin, causing its retention in the blood, and imaging of lung cancer, liver cancer, and other types of cancer would be difficult because of the large [123I]BMIPP accumulation in the heart, blood, and other trunk tissues." (PMID 39062992, 2024). "Albumin, which was identified as a risk factor for overall cancer, pancreas cancer, malignant melanoma, prostate cancer, and leukemia, was found to be negatively associated with specific cancer types such as liver cancer, lung cancer, bladder cancer, and multiple myeloma." (PMID 39003294, 2024). "Meanwhile, the association of serum albumin levels with lung cancer risk may differ by race." (PMID 35814479, 2022). "The high tissue retention associated with albumin nanoparticles may be useful for therapeutic regimes such as lung cancer treatment with inhaled nanomedicines, which would benefit patients by providing high, sustained drug concentrations in the lung tissue and low systemic drug exposure." (PMID 25980621, 2015). "Our findings suggest that certain OSIBs, such as Albumin, MUFA, and Lactate, are significantly associated with lung cancer risk." (PMID 40719999, 2025). "Among the inflammatory indices, C-reactive protein/albumin ratio (p=0.002), advanced lung cancer inflammation index (p=0.04), and neutrophil/lymphocyte ratio (p=0.008) were associated with overall survival." (PMID 40465984, 2025). "The ALI, a composite index that integrates measures of inflammation and nutrition, including BMI, serum albumin, and the neutrophil-to-lymphocyte ratio (NLR), was initially used to assess the mortality risk in lung cancer patients." (PMID 40655483, 2025). "Random forest modeling identified body mass index (BMI) and albumin (ALB) as key components of the advanced lung cancer inflammation index (ALI)." (PMID 40218080, 2025). "Our results revealed that albumin levels are a prognostic factor for length of hospital stay in male patients with lung cancer undergoing chemotherapy, despite the occurrence of many adverse events." (PMID 40786260, 2025). "This study demonstrated that albumin levels during hospital admission serve as an independent predictor of prolonged hospitalization in older male patients with lung cancer undergoing chemotherapy." (PMID 40786260, 2025). "The present study aimed to evaluate the ability of a laboratory cachexia score (LCAS) defined by LDH, CRP and albumin, to identify cachexia and predict outcome in advanced lung cancer." (PMID 40133911, 2025). "Similar patterns were found in lung cancer, renal cell cancer and melanoma with cachexia, WLGS of 4, NLR > 3, albumin <3.5 g/dL and PNI < 44 being associated with lower disability‐free, hospitalization‐free and overall survival rates." (PMID 39817619, 2025). "Patients (n = 261) with serum LDH, CRP and albumin measurement receiving palliative radiotherapy for advanced lung cancer between 2009 and 2015 were identified." (PMID 40133911, 2025). "These key features included activities of daily living (ADL), alkaline phosphatase, oxygen saturation, lactate dehydrogenase, non-lung cancer, respiratory rate, blood urea nitrogen, pulse rate, C-reactive protein, albumin, and systolic blood pressure." (PMID 40777144, 2025). "Advanced Lung Cancer Inflammation Index is calculated by multiplying BMI by serum albumin and dividing by NLR." (PMID 40777182, 2025). "NNK injection significantly decreased serum total protein and its fractions, albumin, and globulin in lung cancer control rats by about 25.70, 24.85, and 26.34%, respectively, compared to the negative control (p ≤ 0.05)." (PMID 39338293, 2024).
lung cancer (continued). "The bioinformatics-based association analysis identified candidate exosomal proteins associated with lung cancer, including SPP1, CD44, ALB, SPARC, CAT, GAPDH, and CADM1." (PMID 39766023, 2024). "Albumin treatment is beneficial as a natural lung surfactant, and it was shown that inhalable albumin-based nanoparticles exhibited excellent potency in lung cancer and was drug-resistant." (PMID 39459897, 2024). "This research examines the cytotoxic consequences of thymoquinone-loaded bovine serum albumin nanoparticles (TQ-BSA NPs) on the A549 lung cancer cell line." (PMID 39655191, 2024). "We found ALP levels positively associated with lung cancer risk, whereas ALT, TBIL, ALB, and AST were inversely correlated; TP exhibited a U‐shaped association, whereas GGT displayed a mirrored J‐shaped relationship." (PMID 39721983, 2024). "Due to the characteristics of rapid metabolism and proliferation of tumor cells, nutritional status indicators such as BMI and albumin are also important clinical prognostic parameters for evaluating lung cancer treatment." (PMID 38877553, 2024). "Statistical analysis shows that there are significant differences in Hb, serum iron, C‐reactive protein, albumin, and total cholesterol in 1040 patients with lung cancer CRA (p < 0.01)." (PMID 38562035, 2024). "Analysis indicated that CRP, albumin, total cholesterol, and cancer staging were primarily associated with CRA incidence in lung cancer patients with normal serum iron levels (p < 0.05)." (PMID 38562035, 2024). "Docetaxel and paclitaxel (conventional and albumin-bound), are common antimicrotubule inhibitors used in the treatment of lung cancer." (PMID 39302574, 2024). "The C-reactive Protein to Albumin Ratio has been demonstrated to predict unfavorable outcomes in colorectal cancer, oral squamous cell carcinoma, gallbladder cancer, lung cancer, and thoracic esophageal cancer." (PMID 38500655, 2024). "Building on this, our study introduces the lung cancer oxidative stress indicator OSS, which includes ALB, TBIL, BUN, UA, LDH, and Crs, all closely linked to oxidative stress." (PMID 39507753, 2024). "This study utilizes multivariate logistic regression analysis to identify the related influencing factors that affect the occurrence of CRA in lung cancer patients with decreased serum iron, which include albumin, age, and cancer staging." (PMID 38562035, 2024). "The association between pretreatment albumin-to-alkaline phosphatase ratio (AAPR) and clinicopathological parameters and prognosis in lung cancer is unclear." (PMID 38216656, 2024). "The top candidate exosomal proteins associated with lung cancer, based on the number of publications supporting the association, included SPP1, CD44, ALB, SPARC, CAT, GAPDH, and CADM1." (PMID 39766023, 2024). "Advanced lung cancer inflammation index was calculated as BMI (kg/m2) × serum albumin level (g/dL)/neutrophil to lymphocyte ratio (NLR)." (PMID 37206362, 2023). "Adequate albumin levels are described as a prognostic factor in several types of malign tumors including lung cancer." (PMID 36624406, 2023). "Another study also reported that High BAR was a stronger predictor of in-hospital mortality than either BUN or serum albumin in ICU patients with lung cancer." (PMID 38222193, 2023). "Preoperative serum markers, including blood urea nitrogen (BUN) and albumin levels, have been studied as prognostic factors for lung cancer surgery." (PMID 38222193, 2023). "The key influencing features for predicting the risk of ED visits in the LGBM model were identified as recent ED visits, elapsed days since the initial diagnosis for lung cancer, the use of analgesics, and lymphocyte and albumin levels." (PMID 38055320, 2023). "The advanced lung cancer inflammation index, an index that combines body weight, albumin and neutrophil to lymphocyte ratio (NLR), was originally used to assess systemic inflammation levels in cancer patients." (PMID 37206362, 2023).